RN7SL447P (RNA, 7SL, cytoplasmic 447, pseudogene)
Gene: Miscellaneous RNA gene on chromosome 3 (193,740,471 to 193,740,715, reverse strand). Ensembl gene ENSG00000243991.
Homologues: Orthologues: chimpanzee Metazoa_SRP (84% identical), macaque Metazoa_SRP (67% identical). Paralogues in human: RN7SL2 (75% identical), RN7SL1 (73% identical), RN7SL518P (73% identical), RN7SL3 (73% identical), RN7SL664P (73% identical), RN7SL769P (73% identical), RN7SL122P (72% identical), RN7SL45P (72% identical), RN7SL482P (72% identical), RN7SL597P (72% identical), RN7SL786P (72% identical), RN7SL118P (72% identical), and 701 more.